IL33 (interleukin 33)
Diseases named in the same sentence as IL33 in open-access papers (continued):
Sharing a sentence is not in itself a finding about the gene and the disease.
Sepsis (continued). "In summary, sepsis induces ILC2p egress from BM and this egress requires downregulation of CXCR4 expression by IL-33 during sepsis." (PMID 35272622, 2022). "S100A9; LBP; soluble ST2 (sST2), which serves as a decoy receptor for IL-33; and RAGE (also known as AGER) have been used as prognostic biomarkers in sepsis." (PMID 33232303, 2021). "Although IL-33/ST2 signaling in ILC2s was robust, IL-13 secretion remained low during the early phase of sepsis." (PMID 33053762, 2020). "To further investigate the molecular mechanism underlying the regulatory roles of sesamin in the inflammatory effects on sepsis, we used RT-qPCR and Western blotting to evaluate the HMGB1/TLR-4/IL-33 signalling pathway." (PMID 32893702, 2020). "In the current study, we demonstrate for the first time that IL-33 plays a role in regulating the production of PGE2, IL-17A, and IL-22 in septicemia." (PMID 33178181, 2020). "Another 5–10-month follow-up study in sepsis patients showed an increased frequency of circulating FOXP3+ T cells, along with higher concentrations of IL-33 and IL-10 in their serum when compared to healthy controls." (PMID 33336293, 2020). "Model mice were treated with IL-33 or its receptor ST2 in order to determine the effects of IL-33 on IL-17A, IL-22, and PGE2 in septicemia." (PMID 33178181, 2020). "The data presented here show that IL-33/ST2 signaling leads to a significant expansion of ILC2 cells in the lungs and peritoneal cavity following CLP-induced sepsis." (PMID 29511181, 2018). "An increasing body of evidence indicates that the IL-33/ST2 axis is involved in the initiation and progression of sepsis." (PMID 28387719, 2017). "Collectively, these data indicate that IL-33/ST2 and IL-4/IL-13/STAT6 signalling are required for the expansion of Treg cells in sepsis-surviving mice, linking IL-10-secreting M2 macrophage in this process." (PMID 28374774, 2017). "Although IL-33, a member of the IL-1 family, was the first molecule described to preserve CXCR2-mediated migration of neutrophils in sepsis, we found that the fibrate-mediated stabilization of CXCR2 occurred independently of this IL-33-mediated pathway." (PMID 24755316, 2014). "IL-33 also promotes NK cells’ activation in septic mice, and IL-33 treatment has a beneficial role in the early stages of sepsis but not in the late phases." (PMID 40429966, 2025). "The observed pattern mirrors the biphasic immunopathology seen in sepsis, where MASLD patients exhibited higher baseline levels of IL17A, IL-23, IL-33, CXCL10 and TGF-β1, yet experienced steeper declines in in IL-10, IL-23, CXCL10 and TGF-β1 in comparison to non-MASLD counterparts." (PMID 40869413, 2025). "In a similar study, in the mouse model of sepsis, IL-33 administration enhanced neutrophil inflow to the site of infection and played a biological role, thereby effectively curing and reducing mortality in CLP-induced sepsis mice." (PMID 39925809, 2025). "In addition sepsis is accompanied by a cytokine storm, and interleukin-6 IL-6), IL-8, IL-1β, IFN-α2, and IL-33 are released." (PMID 38279209, 2024). "In addition, IL-33 facilitates the level of macrophage pyroptosis by activating the NF-κB/p38 MAPK signaling pathway and increases the mortality of mice with sepsis." (PMID 39991638, 2024). "Clinical data have shown elevated serum levels of IL-33 or sST2 in adult patients with sepsis, whereas more serum sST2 levels were present in the non-survivors compared to the survivors." (PMID 39991638, 2024). "Furthermore, reduced IL-33 level in aging mice contributes to impaired ILC2p mobilization from BM, as well as ILC2 recruitment to lung following sepsis." (PMID 35272622, 2022). "Since IL‐33 levels were not increased in the control group, we analyzed the 13 patients with sepsis who had increased circulating IL‐33 levels." (PMID 35593197, 2022).
Sepsis (continued). "Importantly, we demonstrate that reduced IL-33 level in aging mice contributes to impaired ILC2 mobilization from BM and accumulation in the lung following sepsis." (PMID 35272622, 2022). "At present, the regulatory effect of IL-33 on thepyroptosis of macrophages through the NF-κB/p38 MAPK signaling pathway has not beenstudied in the case of sepsis." (PMID 34133503, 2021). "Using IL-33 as a therapeutic target and inhibiting the MAPK/NF-κBsignaling pathway may become a possible way to treat severe inflammatory diseases,such as sepsis in the future." (PMID 34133503, 2021). "Theregulatory role of IL-33 in the first and second signals of inflammasomes duringpyroptosis of macrophages in sepsis was not investigated deeply, which will be thedirection and focus of subsequent studies." (PMID 34133503, 2021). "Other biomarkers that can indicate the immune state in sepsis patients include apoptosis markers (Bim, Bid and Bac), caspases, leukocyte markers (HLA-DR, PD-1, FOXP3, CD127) and cytokines (IL-2, IL-6, IL-12, IL-17, IL-22, IL-33, TNF-α, IFN-γ, IL-10 and TGF-β)." (PMID 33336293, 2020). "IL-33-mediated ILC2 activation induces lung eosinophilia and reduces S. aureus-induced neutrophilia, thereby balancing dysregulated septic inflammation and reducing sepsis mortality." (PMID 33053762, 2020). "IL-33 signals through the cytokine receptor ST2 and plays an anti-inflammatory role during sepsis, improving survival during the early stages of sepsis but ultimately leading to long lasting immunosuppression through the induction of regulatory T cells (Tregs)." (PMID 31507598, 2019). "Decreased levels of IL-10 and IL-33 indicate that blocking CX43 might improve the long-term outcomes, as these cytokines have been shown to be involved in immunosuppression following sepsis." (PMID 30735126, 2019). "Our data showed that genetic deficiency of Il-33 prevented ILC2 expansion in the lung and increased MLEC death following CLP-induced sepsis; and addition of IL-33 into MLEC did not affect MLEC death in response to LPS and TNFα." (PMID 29511181, 2018). "However, both Il-33−/− and Il1rl1−/− mice exhibited reduced levels of IL-9 and IL-13 in plasma and bronchoalveolar lavage fluid (BALF) after sepsis as compared with those in WT mice." (PMID 29511181, 2018). "Although sepsis-surviving Il1rl1−/− mice had higher production of IL-33 than WT mice, they failed to produce more IL-4 and IL-13 in the lungs compared to the naive control mice at day 15 after CLP." (PMID 28374774, 2017). "Peripheral blood from sepsis survivors was collected 5–10 months after sepsis diagnosis and analysed for the frequency, and the absolute number of CD4+Foxp3+ T cells and serum concentration of IL-33 and IL-10 together with age- and sex-matched healthy volunteer blood donors (n=14)." (PMID 28374774, 2017). "Nevertheless, we observed an increasing production of type 2 cytokines (IL-4 and IL-13) and IL-33 in the lung tissue homogenates and bronchial lavage (BAL) fluids of sepsis-surviving mice at later time points, starting at day 3 after CLP and remaining elevated over the course of observation." (PMID 28374774, 2017). "Furthermore, neutralization of IL-33 with soluble ST2 (sST2, a decoy receptor for IL-33) limits the immunosuppressive effect of sepsis and reduces mortality of mice affected by secondary infection." (PMID 28374774, 2017). "During late-stage sepsis, TIGIT-expressing Foxp3+ Tregs exhibit enhanced suppressive function dependent on the IL-33/ST2/STAT6/M2 macrophage axis, suggesting that IL-33 or anti-TIGIT therapy may represent a promising strategy for the treatment of immunosuppressive sepsis." (PMID 40806563, 2025). "In the same category, IL-33 had a negative correlation with sepsis severity." (PMID 40429966, 2025). "Notably, IL-33 shows a positive correlation with PCT levels and severity of sepsis." (PMID 41300951, 2025).
Sepsis (continued). "Additionally, IL-33 has been shown to prevent cardiomyocyte apoptosis, improve cardiac function and survival post-myocardial infarction via ST2 signaling, and reduce mortality in experimental sepsis by enhancing neutrophil influx to infection sites." (PMID 39650246, 2024). "However, how IL-33 regulates ILC2 recruitment into the lung following sepsis has not been determined." (PMID 35272622, 2022). "Since the discovery of interleukin-33 (IL-33) in 2005 as the ST2L ligand, the molecule has been deeply considered in inflammatory conditions, fibroproliferative diseases, autoimmune diseases, trauma, sepsis, and most recently and significantly in pulmonary and cardiovascular diseases." (PMID 35897800, 2022). "While many reviews have discussed the therapeutic potential for targeting IL-17, IL-27, and IL-33 during sepsis, none have considered the effect that treatment targeting only one of these cytokines may have on the others." (PMID 31507598, 2019). "It is currently unknown how much IL-33 signaling changes during sepsis in the absence of IL-27 signaling and therefore might lower the efficacy of IL-27 blockade in improving long term survival in sepsis patients who receive no further interventions." (PMID 31507598, 2019). "Given the fact that IL-33 activates dendritic cells during antigen presentation and promotes their recruitment, our data implicate the crucial role of ST2 receptor signaling in dendritic cells maturation and subsequent development of protective immune response in sepsis." (PMID 30001716, 2018). "This ‘trade-off' could also explain why blocking IL-33/ST2 signalling could not completely protect the sepsis-surviving mice from the secondary challenge infection." (PMID 28374774, 2017). "Thus IL-17A may contribute to sepsis progression, like IL-33 and CRTH2, which are potential therapeutic targets for polymicrobial sepsis." (PMID 27389701, 2016). "However, previous studies have shown that non-detectable levels of IL-33 and soluble ST2 levels above the median dramatically increased the 30-day mortality risk in critically ill patients, and that serum ST2 levels correlate with sepsis severity." (PMID 33178181, 2020). "Interestingly, IL-33 reduced systemic but not local proinflammatory responses by reducing the concentration of blood and lung cytokines, and thereby limiting the systemic inflammation induced by sepsis." (PMID 29728738, 2018). "IL-1beta, IFN-α2, IFN-γ, TNF-α, IL-8, IL-33, IL12p70, IL-17A, and IL-23 do not show significant differences between the sepsis groups or compared to healthy controls at d0, suggesting these markers may not play a central role in distinguishing between sepsis types." (PMID 40510342, 2025). "The same was observed when IL-33, the cytokine favoring neutrophil CXCR-2-dependent infiltration during sepsis, was blocked by a neutralizing antibody (data not shown)." (PMID 33673387, 2021). "Although ILC2s are not regulated by IL-33/ST2 and PD-1/PD-L1 signaling alone, these signaling mechanisms are crucial regulators for ILC2s in sepsis-induced lung inflammation." (PMID 33053762, 2020). "Conversely, sepsis-surviving mice lacking ST2 or STAT6 do not show polarization of M2-like macrophage, indicating that type 2 cytokines and IL-33 are critically involved in the polarization of M2 macrophages in sepsis-surviving mice." (PMID 28374774, 2017). "While IL-33 can bind to a soluble form of ST2 (sST2), the effects of IL-33 during sepsis appear to be dependent on signaling through membrane bound ST2; in one study, patients who had did not survive sepsis had higher levels of sST2 than patients that went on to survive their infections." (PMID 31507598, 2019).
atherosclerosis (88 papers, 2008 to 2026). A disease characterized by the build-up of fatty material and calcium deposition in the arterial wall resulting in partial or complete occlusion of the arterial lumen. "Treatments that target interleukins, such as IL-27, IL-28, IL-29, IL-31, IL-32, and IL-33, have shown promise in reducing fibrosis and inflammation, two important processes linked to the development of heart disorders such as atherosclerosis and heart failure." (PMID 39844544, 2025). "IL-33, found in the blood vessels, has been linked to offering numerous safeguards against atherosclerosis and heart fibrosis." (PMID 39844544, 2025). "Combined, these results suggest a potential protective effect of the IL-33 rs3939286 T allele in atherosclerosis development by decreasing IL-33 expression." (PMID 35600479, 2022). "The role of IL-33 has been implicated in various cardiovascular diseases, including atherosclerosis." (PMID 36552551, 2022). "When interfering the OX40–OX40L pathway by treatment with anti-OX40L in LDL receptor-deficient mice, an increase in IL-33 expression in the spleen of treated mice compared with control mice in parallel to the regression of atherosclerosis was observed." (PMID 34948083, 2021). "Association of IL-33 and sST2 with the pathogenesis of atherosclerosis and thrombosis has been demonstrated in several previous studies." (PMID 33415128, 2020). "Further studies are required given the important roles of genes whose expression is inhibited by IL-33 in key cellular processes associated with atherosclerosis such as monocyte recruitment, foam cell formation and lipoprotein metabolism." (PMID 31383884, 2019). "Animal studies have indicated that IL-33 reduces macrophage foam cell formation and inhibits the development of atherosclerosis in apolipoprotein E-deficient mice." (PMID 28045954, 2017). "Previous work demonstrated that the systemic administration of recombinant IL‐33 reduces the development of atherosclerosis in apolipoprotein E‐deficient (ApoE−/−) mice by inducing a Th1‐to‐Th2 shift." (PMID 26417439, 2015). "Of note, the administration of recombinant IL‐33 exerted a protective effect in the apolipoprotein E‐deficient (ApoE‐/‐) mouse model of atherosclerosis." (PMID 26417439, 2015). "Although IL-33/IL1RL1 interaction has been suggested to be important in the development of atherosclerosis, genetic influences of the polymorphisms of IL33 in human ischemic stroke are unclear." (PMID 24107076, 2013). "Recently, it has been reported that IL-33/ST2 pathway can protect against atherosclerosis and adipose tissue inflammation which are well-known risk factors for ischemic stroke." (PMID 24107076, 2013). "In addition, it was found that certain genetic polymorphisms in the IL-33 locus resulted in deferential atherosclerosis development in patients with RA." (PMID 35600479, 2022). "It has been speculated that IL-33 reduces the risk of plaque rupture by inhibiting the immune response involved in atherosclerosis, an effect that can be reversed by sST2." (PMID 32886697, 2020). "Previous findings also showed that the reduced level of IL-33 might increase the risk of atherosclerosis development for certain individuals." (PMID 30761089, 2019). "Interestingly, our results suggest a potential protection effect of the mutant IL33 rs3939286T allele in the risk of subclinical atherosclerosis, established by the assessment of cIMT, in patients with RA." (PMID 26571131, 2015). "In conclusion, our results may suggest a potential protective effect of the IL33 rs3939286 allele T in the risk of subclinical atherosclerosis in patients with RA." (PMID 26571131, 2015). "Our data support previous findings showing a protective role for IL-33 against adiposity and atherosclerosis, and further suggest that reduced levels of IL-33 may put certain individuals at increased risk of developing atherosclerosis and insulin resistance." (PMID 24886535, 2014).
atherosclerosis (continued). "Accordingly, recombinant IL-33 was found to drive production of pro-inflammatory and Th2-associated cytokines in mast cells and Th2 lymphocytes, to induce chemotaxis of Th2 cells and to protect the heart against cardiac stress and atherosclerosis." (PMID 18836528, 2008). "Therefore, IL-33 may serve as a novel marker to predict those who may be at increased risk of developing atherosclerosis." (PMID 24886535, 2014). "One possible additional way IL-33 reduced atherosclerosis is by helping to prevent the creation of macrophage foam cells through its action." (PMID 39844544, 2025). "Although neutrophils infiltration destabilizes the atherosclerotic plaque, the interplay between VSMCs, neutrophils and IL-33 in atherosclerosis is not fully understood." (PMID 38519881, 2024). "IL-33, an IL‐1‐related cytokine is known to augment sterile inflammation in cardiovascular diseases including atherosclerosis." (PMID 38519881, 2024). "In vivo supplementation of IL-33 to reverse atherosclerosis is a topic for future research to clarify the validity of this study." (PMID 38674885, 2024). "IL-33 has a potent immunomodulatory and anti-atherosclerosis function, which belongs to the IL-1 family from previous studies." (PMID 39765815, 2024). "The use of HAECs to elucidate the relationship between atherosclerosis and IL-33 revealed a significant increase in arterial IL-33 levels in ApoEKO mice." (PMID 38674885, 2024). "The aim of this article is to summarise current evidence that HMGB1, S100 proteins, and IL-33 play roles in the pathogenesis of atherosclerosis and myocardial infarction." (PMID 39194749, 2024). "The understanding of the role of the IL-33/ST2L/sST2 system in atherosclerosis underwent a paradigm shift since the description of IL-33 as a new member of the IL-1 superfamily in 2005." (PMID 37240352, 2023). "The research by Miller also shows that the IL-33/ST2 signaling pathway seems to be involved in the mechanism of atherosclerosis as the administration of IL-33 in ApoE mice on a high-fat diet was related to the reduction of plaque size in the aortic sinus." (PMID 36407452, 2022). "In recent years, the role of NETs has been widely implicated in the pathogenesis of cardiovascular diseases, including atherosclerosis; however, the impact of IL-33 on neutrophil function, particularly on NET formation, has not been defined in aAT patients." (PMID 36552551, 2022). "Other than its role in atherosclerosis, IL-33 exerts a protective effect in most infectious settings, by assisting the clearance of the causal microorganism." (PMID 36555579, 2022). "Relevant cytokines involved in Treg activation and recruitment are elevated in P2Y4 KO mice after MI, such as IL33 that stimulates Treg cells and regulates T cell expansion to reduce the formation of atherosclerosis plaque." (PMID 36248854, 2022). "The Treg cell-mediated protective role of IL-33 on atherosclerosis and lipid homeostasis has been discussed; however, growing evidence suggests that IL-33 induces an inflammatory response in ECs." (PMID 34445530, 2021). "IL-33 can promote helminth infection and alleviate atherosclerosis by promoting Th2 immune response." (PMID 34395633, 2021). "Some previous findings regarding IL-33 concentration reported its useful effect on cardiovascular disorders such as cardiac fibrosis, atherosclerosis, hypertrophy, and diabetes." (PMID 34754275, 2021). "The effect of IL-33 on the function of foam cells indicated the protective role of IL-33 in atherosclerosis." (PMID 33608010, 2021). "IL-33 has been shown to exert protective effects in atherosclerosis mice through a switch from a pro-atherosclerotic Th1type to a protective Th2 type immune response." (PMID 32286393, 2020). "Another possible mechanism linking the ST2/IL-33 axis to CAD outcomes is its correlation with atherosclerosis progression and plaque destabilization." (PMID 32886697, 2020).